IL4 (interleukin 4)
Diseases named in the same sentence as IL4 in open-access papers (continued):
Sharing a sentence is not in itself a finding about the gene and the disease.
infection (continued). "On the other hand, BALB/c susceptible mice are more prone to produce a Th2 immune response with the presence of IL-4, IL-5, and IL-13; IL-4−/− BALB/c mice were capable to partially control the infection with some strains of L. major." (PMID 25505469, 2014). "In the first cultures after infection (6–13 dpi), the IFN-γ/IL-4 ratios were low, with mean values ranging between 2.3 ± 1.2 and 3.3 ± 2.8 in G1 and 5.3 ± 8.7 and 8.0 ± 5.1 in G2." (PMID 24479988, 2014). "We found similar results with primary T cell lines from deer mice at 10 days post infection with SNV, in which Ifng, Il4, Il5, Il10 and Tgfb were elevated." (PMID 23570545, 2013). "It is not possible, however, to quantitatively distinguish the importance of the early reduced IL-10 secretion from the likewise reduced IL-4 secretion and increased IFN-γ secretion following infection." (PMID 23825956, 2013). "At eight weeks post infection, the percentages of CD4+ IFN-γ+ and of CD4+ IL-4+ T cells were also similar, whereas the percentage of CD4+ IL-10+ T cells was significantly lower in Linb-11-immunized mice." (PMID 23717705, 2013). "After 4 weeks of infection, DLN cells of L. major-infected UCP2KO mice produced significantly lower levels of SLA-specific IL-4 than those of WT mice, but they produced significantly larger amounts of SLA-specific IFN-γ and IL-17." (PMID 23437414, 2013). "One important difference is that infection leads to the establishment of permanently growing lymphoblastoid cell lines, whereas CD40L/IL-4 blasts have finite proliferation lifespans." (PMID 23724103, 2013). "While the IL-4 level was stable across the HIV-negative population, it appeared to fluctuate in the HIV-infected population according to their infection status with different parasite species." (PMID 23971713, 2013). "Taken together, some proportion of the hepatic CD4+ T cells in the liver during the transition phase of the infection indeed acquired the capacity for producing IFN-γ, IL-13, and IL-4 simultaneously (“triple positive cells”)." (PMID 24358216, 2013). "On the other hand, IL-2 and IL-4 levels in TNF-α KO mice were significantly higher than those of WT and IL-10 KO mice during mock infection and following JaOArS982 infections." (PMID 23940775, 2013). "Gene expression studies have shown increased expression of IFNγ, IL12p40, Perforin, IDO, IL-4, IL-10, and forkhead box p3 (FOXP3) in infection and/or disease, with levels generally being highest if both were present." (PMID 23457650, 2013). "At 3 dpi, IL-4, IL-6 and TNF were upregulated similarly in response to both virus strains and remained upregulated throughout the course of infection." (PMID 23342177, 2013). "The aim of this study was to characterize the in vivo plasma concentrations of the cytokines TNF-α, IFN-γ, IL-4, IL-10 and the overall role of CD4+ T cells in the development of cytokine levels during a primary infection." (PMID 22533922, 2012). "those that are highly upregulated only by infection with virulent S. flexneri (CCL4, CCL20, IFN-γ, IL-1β, IL-4, IL-6, IL-8, IL-12/23p40, IL-21, TNF-α, CAP-18, LeukoP and COX-2); ii." (PMID 22675469, 2012). "Wild type mice resist infection with N. brasiliensis and develop polarized TH2 responses with high IL-4/IL-13 and low IFN-γ production." (PMID 23284939, 2012). "Therefore, the increased IL-4 production from Laiscl−-infection may be the consequence, rather than the cause of reduced virulence." (PMID 23285302, 2012). "After boosting immunization or 4 days post-infection with PR8, homologous and heterologous T-helper cell responses were evaluated by mouse IL-4 (Th-2) and IFN-γ (Th-1) ELISpot analyses." (PMID 22879951, 2012). "CD4 T cells purified from the mediastinal lymph node (MedLN) and spleen on day 10 after NC infection of DR1 mice were tested for their ability to secrete IL-2, IFN-γ, or IL-4 after stimulation with defined peptide epitopes." (PMID 22457834, 2012).
infection (continued). "However, this pathogen may uses other mechanisms to circumvent host-cell defenses and establish infection by dowregulating other adaptive immune response genes such as IL-2 and IL-4 and delaying the apoptotic death of neutrophils through activation of the Jak-STAT pathway." (PMID 22935149, 2012). "Twelve weeks post-infection, the expression levels of IFN-γ, IL-4, IL-10, TNF-α and Arg I were similar in both groups." (PMID 21390155, 2011). "Higher levels of IL-4 expression also correlate with heightened immune responsiveness to ESAT-6, a proxy marker for infection in TB contacts and for bacterial load." (PMID 21253484, 2011). "The production of IL-1β, IFN-α, IL-10, TGF-β, IL-4 and TNF-α by the nervous tissues of infected animals increased significantly at different times after infection." (PMID 21813860, 2011). "Our data showed that at day 15 post-infection, the CFA-inoculated mice produced significantly higher amounts of IL-4 and diminished IFN-γ production in the indicated organs." (PMID 21731741, 2011). "Alternatively, the observed association of IL4 polymorphism and infection intensities could be due to linkage disequilibrium of IL4 with other genes such as IL13 and IL5, which in humans are located just 12.5 kb and 132 kb upstream of IL4 and are also key TH2 cytokines." (PMID 21501512, 2011). "The infection with pH1N1 resulted in considerable decrease in the expression of cytokine and other immune genes namely IL8, STAT1, B2 M and IL4 compared to seasonal H1N1." (PMID 21439068, 2011). "In case of challenge infection, HPB regimen showed almost 2.35 fold and 2.28 fold reductions in IL-4 in STP and LTP studies respectively compared to control PBS." (PMID 21311597, 2011). "Following contact with microbial antigens or their infection, macrophages acquired increased levels of surface CD23, but the phenomenon was potentiated by IFN-γ or IL-4 at transcriptional level." (PMID 21526166, 2011). "Following infection with 200 Trichuris eggs (high dose), wild-type C57BL/6 (WT) mice develop a polarized CD4+ Th2 cell response characterized by high levels of IL-4, IL-5 and IL-13." (PMID 21573179, 2011). "Comparatively weak expression of mRNA for IL-4 was recorded in both UGT and LGT, but the latter showed higher levels on day 15 following infection." (PMID 21079691, 2010). "At the acute stage of infection, besides IFN-γ, the expression of IL-4 and IL-10 in the Vac-Cha group increased significantly at week 6 post-challenge." (PMID 20976218, 2010). "IL-4 up-regulates the expression of HIV mRNA within the first two days after infection of promonocytic U937 cells and 3 to 4 days after infection of plastic-adherent blood-derived macrophages with HIV-1." (PMID 20380696, 2010). "At week 6 post-infection, IFN-γ, IL-4 and IL-10 levels also showed a dramatic rise synchronously in vaccinated pigs." (PMID 20976218, 2010). "Next, we measured the ex vivo and in vitroproduction of IL-4 by CD4+ T cells in draining lymph nodes of BALB/c and CBA mice two weeks post infection." (PMID 19292771, 2009). "We analyzed the levels of IL-2, IL-4, IL-5, IL-10, IL-12(p70), GM-CSF, IFN-γ and TNF-α in the culture supernatant of macrophages 24 h post infection." (PMID 19680450, 2009). "In general, single FIVC infection elicits an overall increase in IL10, IL4, and IL12, but lower expression of CD25, and CD8 throughout the first 31 days of infection (day 31–59 of the experiment) compared to other groups." (PMID 19806226, 2009). "The L. casei group showed levels of IL-10 and IL-4 in BAL and serum significantly higher that those in the control group during the late stage of the infection." (PMID 19835595, 2009). "Our study suggested that circulatory cytokines, namely, IL-4, IL-8, and adhesive molecules like ICAM-1 were enhanced after infection with C. pneumoniae whereas in contrast to this IL-10 and IFN-λwere lowered." (PMID 19360108, 2009).
infection (continued). "This is reflected in later patency of infection, lower peak parasitaemia, and increases in the number of IFN-γ+ and IL-4+ CD4+ T cells in the blood stage of infection in mice given first non-infectious bites." (PMID 17555592, 2007). "Two weeks following infection, the IFN-γ to IL-4 ratio is two-fold higher in animals inoculated with PBS when compared to mice immunized with SGS." (PMID 18060088, 2007). "As shown inFigures 1(a) and 1(b), CXCL-8 mRNA and CXCL-10mRNA were expressed after infection with M. bovis BCG,and IL-4 reduced gene expression of CXCL-8 in M. bovisBCG-infected HEp-2 cells but not CXCL-10gene expression." (PMID 16864907, 2006). "IL-4 production during HSV infection has in vaginal and CNS infections been demonstrated on day 2 of infection and to increase for the next days." (PMID 16076403, 2005). "TNF-α, IL-2, IL-4, IL-10, and IL-12p70 were not produced at 4 h post-infection with any of the bacterial strains, in either HT-29 or Caco2 cell lines (data not shown)." (PMID 41459941, 2026). "Upon challenge infection, elevated IgG- and IgA-secreting plasma cells, germinal center B cells, and memory B cells were observed, and CD4+, CD8+ T-cells, as well as both Th1 (IFN-γ) and Th2 (IL-4, IL-5) cytokines, were also increased." (PMID 41599200, 2026). "Canonical discriminant analyses (CDA) indicated that IP-10, IL-4, IL-17, and TNF could be useful biomarkers for infection status." (PMID 41822517, 2026). "IgE and IL-4 initially do not serve as correlates of protection because they are characteristic of Th2 immune responses and are not protective upon infection by parasitic worm helminths." (PMID 40563507, 2025). "In the CsCP3-immunized group, expression levels of IFN-γ, IL-2, IL-4, and IL-10 rose rapidly post-infection but subsequently dropped to levels not significantly different from the control by the second or fourth week." (PMID 40248698, 2025). "Further validation via Western blot analysis indicated that protein expression levels of IFN-γ, IL-4, IL-6, IL-17, TGF-β, GATA-3, T-bet, RORγt, and FoxP3 were significantly increased in the Pm_OMVs-infected group at 24 hours post-infection relative to the Pm group (P < 0.01)." (PMID 41306977, 2025). "Conversely, at 72 hours post-infection, the secretion of IL-6, IL-17, T-bet, TNF-α, and IFN-γ was significantly diminished (P < 0.01), while levels of TGF-β, GATA-3, IL-10, and IL-4 were significantly elevated in the Pm_OMVs-infected group compared to the Pm group (P < 0.01)." (PMID 41306977, 2025). "At 72 hours post-infection, protein levels of IL-17, IFN-γ, T-bet, RORγt, and IL-6 were significantly decreased, whereas TGF-β, GATA-3, IL-4, and FoxP3 protein expression was significantly upregulated in the Pm_OMVs-infected group compared to the Pm group (P < 0.01)." (PMID 41306977, 2025). "The data indicate regulatory roles for IL-4 and TGF-β infection with maSARS-CoV-2." (PMID 40854598, 2025). "Furthermore, HIV-1ADA infection of PBMCs also resulted in a more significant down-regulation of anti-inflammatory cytokines IL-4 and IL-10, compared to HIV-1IndieC1-infection or control uninfected sample." (PMID 40313367, 2025). "Distinct from Th1 and Th17 cells, Th2 cells produce IL-4, IL-13, IL-5, and IL-10, which facilitate cryptococcal proliferation and tissue damage rather than resisting infection." (PMID 41017910, 2025). "The data obtained from the experimental infection of BALB/c mice with L. (V.)guyanensis indicates a Th2-type response profile, with a predominance of IL-4 and the presence of IL-10, which apparently favored swelling progression during the chronic phase of the disease." (PMID 41017914, 2025). "It is therefore possible that IL-4 plays a decisive role in the initial stages of lesion development, while IL-13 promotes a chronic, nonhealing form of the infection." (PMID 39963187, 2025).
infection (continued). "The host immune response to this infection is a predominantly Th2 response phenotype, where upon secondary infection, memory CD4+ T cells rapidly accumulate at the host-parasite interface and secrete IL-4, inducing localized development of alternatively activated macrophages recruited to this site." (PMID 40501701, 2025). "IL‐4, IL‐5, and IP‐10 in all individuals with COVID versus those without infection, regardless of DM status." (PMID 40476695, 2025). "During secondary infection, CD4+ T cell-dependent Th2-type memory is required for host protection against the parasite, which includes the induction and recruitment of alternatively activated macrophage (AAMacs) by IL-4/IL-13." (PMID 40501701, 2025). "While wild-type mice generally did not succumb to infection, they maintained persistent pulmonary load out to at least 5 months, which was lost in Il4/Il13−/− mice." (PMID 40568097, 2025). "This suggests that patients with high IL-4 levels, as in the TARV group, may have a suboptimal immune response due to poor treatment adherence, resulting in less effective infection control." (PMID 40367013, 2025). "To analyze further functional states of THP-1 cells, which might influence the sensitivity for TcpC during an infection with CFT073, we polarized THP-1 cells to M1 and M2 macrophages using PMA/IFNγ/LPS or PMA/IL-4/IL-13, respectively." (PMID 41310197, 2025). "This analysis prompted us to envision the presence of CD44hi CCR6+ IL17-committed γδ T cells in C2, and NK1.1+ IFNγ/IL-4-committed γδ T cells in C7, both unaffected by infection, suggesting their absence of response to CMV." (PMID 38976755, 2024). "In C57BL/6 mice that heal from a primary infection with L. major, IL-10 is necessary for the long-term parasite persistence, and a sterile cure can be achieved in mice lacking both IL-4 and IL-10." (PMID 38543944, 2024). "The relative expression of IL-4 in the negative control without infection was not significantly different from that in the negative control with infection (p > 0.05)." (PMID 39185043, 2024). "Whole-kidney levels of other neutrophil-recruiting (IL-3, GM-CSF) or inhibitory cytokines (IL-4, IL-10) were not significantly altered by androgen exposure at measured time points after infection (data not shown)." (PMID 38206009, 2024). "Conversely, SmLE infection resulted in elevated levels of IL-2, IL-4, IL-5 and IL-6 and a decrease in IL-13 in C57BL/6 but not in BALB/c mice." (PMID 38711063, 2024). "In contrast with IL-4, IL-5, and IL-13, mRNA expression of IL-1β and TNF-α, both considered type 1 cytokines, decreased after infection with RV2, suggesting that RV infection on day 6 of life skewed the response to subsequent heterologous RV infection toward a type 2 phenotype." (PMID 38061015, 2024). "Rounded semi-detached cells were observed after infection with cp strains in both IL-4 and azithromycin-treated Mo-Mφ, while no cytopathic changes were noted for any of the ncp strains (data not shown)." (PMID 37966797, 2024). "Furthermore, we observed a significant increase in TNFα, IL-1α, IL-2, IL-3, IL-4, IL-9, IL-10, IL-12 (P70), IL-17A, and CCL5 on day 4 post-infection in murine macrophages." (PMID 39038037, 2024). "Our data on the cytokine levels align with the importance of the Th1 response, as all three vaccine formulations induced low levels of IL-4 and undetectable levels of IL-10, with high levels of IFN-γ, in immunized mice and remained detectable in the surviving mice even 30 days after infection." (PMID 39796100, 2024). "As expected, IFN-γ- but not IL-4- or IL17A-producing T cells increased significantly in the popliteal lymph node of all groups over the course of infection as the adaptive response was established." (PMID 39076982, 2024). "The data presented within this study also provide evidence that BTV suppresses serum IFN-γ and IL-4 cytokine production in infected sheep, as these cytokines were not detectable in any of the mock-depleted sheep during infection." (PMID 38357545, 2024).
infection (continued). "Following the infection, there was a notable increase in the expression of IFN-γ, IL-4, and IL-8." (PMID 39234535, 2024). "In the negative control group with infection, the expression levels of IL-10 and IL-4 were lower than those in the negative control group without infection and with no bacteria." (PMID 39185043, 2024). "At 24 h post-ex vivo infection, the median percentage differences in cytokine levels were as follows: IL-2 and IL-4 both showed no change at 0%; IL-10 exhibited a significant increase at 104%; TNF-α at 167%; and IFN-γ at 197%." (PMID 39456722, 2024). "IL-4 treatment, which increases tuft cell numbers, also increased barcode richness, indicating the abundance of permissive tuft cells to be a bottleneck during CR6 infection." (PMID 38701091, 2024). "In contrast, the negative control group with infection exhibited a decrease in IL-4 expression, indicating activation of the immune response due to infection." (PMID 39185043, 2024). "Since IL-4 and IL-5 have previously been reported to promote mucus secretion in asthmatic patients, we examined their expression levels in the lung tissues of WT and LincR-PPP2R5C KO mice at 21 days post infection." (PMID 39287443, 2024). "With regard to Th2 and Treg cytokines, infection did not induce a statistical difference in the production of IL-4 or IL-10 when compared to that in the healthy group (IL-4: p > 0.1022; IL-10: p > 0.3939)." (PMID 39598539, 2024). "Infection induced no statistical difference in the production of IL-4 or IL-10 when compared to that in the healthy group (IL-4: p > 0.2547; IL-10: p > 0.4021)." (PMID 39598539, 2024). "To better understand the role of IL-4 in mice, we neutralized IL-4 in WT and LincR-PPP2R5C KO mice with an IL-4 neutralizing antibody and then measured the fungal burden in the organs of infected mice at 14 days post infection." (PMID 39287443, 2024). "Induction of IL-4 after infection of the piglets with JEV was not observable for our analyzed time points." (PMID 39186783, 2024). "The inflammatory cytokines TNFα, IL-4, IL-6, IL-13, IL-10, IL-12 (P40), and IL-12 (P70) along with chemokines including CCL2, CCL3, and CCL5, were significantly elevated in the plasma of c-Flip+/–mice on day 2 post-infection compared that of WT mice." (PMID 39038037, 2024). "Regarding neonatal mouse cardiomyocytes, infection with either of the isolates and stimulation with IL-4 did not significantly increase parasite loads." (PMID 39452749, 2024). "Throughout the infection, we noted that pro-inflammatory factors such as IL-1β and TNF-α consistently increased in both serum and liver tissue, while anti-inflammatory factors like IL-4 and IL-10 showed a continuous decline." (PMID 39749332, 2024). "The infection of cardiomyocytes with T. cruzi isolates, and stimulation with IL-4 did not produce the anticipated effect." (PMID 39452749, 2024). "In our study, chickens challenged with E. tenella infection (G5) exhibited a significant up-regulation of IFN-γ, NO, and IL-4 levels nine days post-infection compared to the negative control group (G8)." (PMID 37736869, 2024). "Interestingly, the ratios of IFN-γ/IL-4 and IFN-γ/IL-10 were elevated in splenocytes and the IFN-γ/IL-10 was elevated in sera of DKO-inoculated animals at later stages of infection indicating they have pro-inflammatory reactivity to parasite antigen." (PMID 37185599, 2023). "After treatment with IL-4/IL-13 at day 1 followed by infection 24 h later, we observed increased intensities of ICP0 stainings compared to untreated cultures supporting enhanced efficiency of infection." (PMID 37289055, 2023). "Our results are in line with results reported in a previous rat model study, where no IL-4 or IL-5 was found in the vaginal fluid after inoculation, while a notable Th1 cytokine pattern was found during the primary infection." (PMID 37529322, 2023).